ZNG1F (Zn regulated GTPase metalloprotein activator 1F)
Description:
Zinc chaperone that directly transfers zinc cofactor to target metalloproteins, thereby activating them (By similarity). Catalyzes zinc insertion into the active site of methionine aminopeptidase METAP1, which function to cleave the initiator methionine from polypeptides during or after protein translation. Mechanistically, the N-terminal psi-PxLVp motif binds to the C6H2-type zinc finger of inactive form of METAP1 (By similarity). After formation of the docked complex, zinc is transferred from the CXCC motif in the GTPase domain of ZNG1F to the zinc binding site in the peptidase domain of METAP1 in a process requiring GTP hydrolysis (By similarity). GTP/GDP exchange is required for release of active METAP1 (By similarity).
Synonyms: CBWD6; CBWD7; OTTHUMG00000066820; OTTHUMG00000067194
Tractability: Antibody: the Human Protein Atlas places it where antibodies can reach. PROTAC: ubiquitination databases record sites on it.
Gene: Protein-coding gene on chromosome 9 (41,131,288 to 41,199,261, reverse strand). Ensembl gene ENSG00000215126.
Subcellular location: Nucleus
Subcellular location (Human Protein Atlas): Plasma membrane
Gene Ontology:
Molecular function: GTPase activity; zinc chaperone activity; zinc ion binding
Biological process: protein maturation
Cellular component: nucleus
Genetic constraint (gnomAD): Loss-of-function variants: 8 observed, 19.3 expected, observed/expected ratio (o/e) 0.41, 90% interval 0.24 to 0.75. The synonymous counts are far from expectation, so gnomAD's model fits this gene poorly and the ratio says little. Missense variants: 73 observed, 136.54 expected, observed/expected ratio (o/e) 0.53, 90% interval 0.44 to 0.65. Synonymous variants: 29 observed, 48 expected, observed/expected ratio (o/e) 0.6, 90% interval 0.45 to 0.82.
Homologues: Orthologues: macaque ZNG1 (97% identical), dog ZNG1 (90% identical), mouse Zng1 (80% identical), rat Zng1a (79% identical), tropical clawed frog zng1b (67% identical), zebrafish cbwd (66% identical). Paralogues in human: ZNG1C (99% identical), ZNG1E (99% identical), ZNG1A (97% identical), ZNG1B (97% identical).